KRAS (KRas proto-oncogene, GTPase)
Diseases named in the same sentence as KRAS in open-access papers (continued):
Sharing a sentence is not in itself a finding about the gene and the disease.
lung cancer (continued). "Increased transversion rates in smokers, thus, may not only be due to the NNK but also increased oxidative stress (OS) in lung cancer cells, suggesting that there may be a link between oxidative stress and KRAS mutational status." (PMID 25222473, 2014). "Another possible implication for the future of precision medicine is that even if newer targeted therapy for BRAF or KRAS mutations was successfully introduced for lung cancer, it may treat only the more aggressive subtype in some tumors." (PMID 24742923, 2014). "Many KRAS-mutant cancer cells have been shown to be sensitive to MEK inhibitors, and KRAS mutations can be detected in up to 30% of lung cancers, dependent upon histology and ethnicity, suggesting that a subset of lung cancers would likely be highly sensitive to AZD6244." (PMID 24939055, 2014). "However, the association of the KRAS-variant with altered miRNA signatures has been found in every tumor in which it has been analyzed, including lung cancer, melanoma, head and neck cancer and triple negative breast cancer." (PMID 24732316, 2014). "Growing evidence supports abnormally activated mTOR to play an important pathogenic role in lung cancer associated with both KRAS and EGFR mutations and may provide a mechanism of resistance to treatment with EGFR inhibitors." (PMID 24593867, 2014). "This may be attributed to the higher prevalence EGFR mutations in lung cancer patients from East than KRAS mutations." (PMID 24533074, 2014). "Moreover, in EGFR mutant or KRAS mutant lung cancer models, tumor regression associated with apoptosis was observed only when the PI3K/AKT pathway and MEK/MAPK pathway were simultaneously blocked." (PMID 24337632, 2014). "Therefore, it is necessary to understand the correlations between EML4-ALK and EGFR/KRAS mutations in lung cancer patients." (PMID 23341890, 2013). "However with the detection of KRAS mutation in lung cancers the drugs are currently under development." (PMID 23863689, 2013). "Since many colon cancer, pancreatic cancer and lung cancers are associated with KRAS mutations, development of drugs targeting PLK1 kinase could be promising in treatment of these cancers." (PMID 24025726, 2013). "KRAS mutations were reported to be almost entirely limited to lung cancers in smokers." (PMID 22675530, 2012). "Both models allow the development of KRAS-mutated lung cancer in a short period of time." (PMID 22022511, 2011). "Variations were found in 18–20% of lung cancer cases as compared to 6% for world population, suggesting a relative risk of 1.4–2.3, and in vitro transfection experiments showed that variant KRAS alleles resulted in increased KRAS protein expression in A549 lung cancer cells." (PMID 20808843, 2010). "Additionally, the variant allele in a KRAS mRNA, associated with a Let-7 miRNA complementary site, is significantly linked with an increased risk for lung carcinoma." (PMID 20507594, 2010). "Furthermore, KRAS-induced lung cancer aggressiveness is associated with GFPT2 expression." (PMID 40830088, 2025). "We asked whether KRAS mutation-positive lung cancers respond to Lac treatment." (PMID 39979425, 2025). "For KRAS-mutant lung cancers in particular, identifying vulnerabilities associated with recurring co-occurring mutations in tumor suppressor genes could enable the development of biomarker-driven combination therapies with enhanced activity in distinct subsets of patients." (PMID 40316540, 2025).
lung cancer (continued). "Additionally, we extended our analysis to lung cancer cell lines harboring upstream KRAS mutations to assess whether the Ba/F3 findings translate to more clinically relevant cellular contexts." (PMID 41282105, 2025). "Additionally, our study reveals a therapy-induced vulnerability in LKB1-deficient KRAS-mutant lung cancers that could be exploited as a genotype-informed strategy to improve the efficacy of KRAS-targeted therapies." (PMID 40316540, 2025). "This may also be one of the mechanisms by which Men1 deficiency promotes KRAS-induced lung cancer." (PMID 40057469, 2025). "Moreover, KRAS-mutated lung cancer with LKB1 deletion exhibits high plasticity." (PMID 40568576, 2025). "It is unclear whether the FLCN mutation contributes to the KRAS mutation in lung cancer." (PMID 40630489, 2025). "The chip could also be used to detect KRAS mutations in plasma samples from lung cancer patients." (PMID 40385463, 2025). "Importantly, treatment of lung cancer cells harboring KRAS mutations with the mTORC1 inhibitor rapamycin restored chemosensitivity of the resistant cells and, combination of rapamycin and chemotherapy showed strong synergistic effect in inhibiting tumor growth." (PMID 39385301, 2024). "Furthermore, combination of ERK5 and CDK5 inhibition with XMD8-92 and Seliciclib, synergize in suppressing FAK and are expected to prevent feedback signaling leading to drug resistance, providing an additional treatment option for lung cancer patients with KRAS mutations." (PMID 39271958, 2024). "Moreover, cases of KRAS mutations were detected in both human lung cancers—NSCLC and SCLC." (PMID 39272828, 2024). "Therefore, FOSL1 activation may serve as a potential target for human lung cancer therapy and a prognostic marker, particularly in cases with KRAS mutations." (PMID 38791400, 2024). "Indeed, the parallel analysis of KRAS mutation and let-7a downregulation may represent a new molecular tool for identifying subjects at high risk for lung cancer to be selected for spiral TAC (early diagnosis and secondary prevention)." (PMID 37511536, 2023). "Moreover, the kinase-independent function of CRAF may be essential for lung cancers with KRAS mutations." (PMID 38111008, 2023). "However, AZ628 might be the potential therapeutic option for CC patients with high risk, which is reported to cause suppression of RAF/ERK signalling in KRAS mutant lung cancer." (PMID 36936374, 2023). "Furthermore, the MAPK pathway could be targeted with new therapeutics, such as specific inhibitors of KRAS G12C mutations that have recently demonstrated meaningful anti-cancer activity in lung cancer with KRAS G12C mutations." (PMID 36900299, 2023). "Therefore, we investigated whether MA, a proven natural inhibitor of PLA2, could inhibit KRAS-mutated lung cancer cells to find a new therapeutic approach for EGFR-TKI-resistant lung cancer cells." (PMID 36712673, 2022).
lung cancer (continued). "However, a more recent study that targeted the G12S mutation variant of the KRAS gene in lung cancer cell line A549 using this CRISPR interference (CRISPRi) system, showed that dCas9-KRAB was outperformed by its wild-type SpCas9 counterpart as a potential therapeutic tool for tumor inhibition." (PMID 36139356, 2022). "Radioresistance in mutated KRAS lung cancers may be related to CSC properties." (PMID 35740495, 2022). "This point is embodied in our study that combinational inhibition of KRAS and NF-κB improved immunogenicity of tumor cells, recruiting effector T cells and thus synergized with PD-1 inhibitors to shrink KRAS mutation positive lung cancer of low ZNF24 expression." (PMID 36457047, 2022). "Moreover, inhibition of NOS2 may have therapeutic value for lung cancer with oncogenic KRAS mutations." (PMID 35256890, 2022). "The mechanisms of radioresistance of mutated KRAS lung cancer cells are still relatively unknown." (PMID 35740495, 2022). "PCDH7 could promote the malignant transformation of bronchial epithelial cells carrying KRAS gene mutation, while knockdown of PCDH7 inhibited the growth and metastasis of lung cancer cells with a mutated KRAS gene, suggesting that PCDH7 and KRAS had a synergistic cancer-promoting effect." (PMID 36117156, 2022). "For NSCLCs harboring KRASG12C mutations (representing more than 40% of the most frequent KRAS mutation in lung cancer), sotorasib, an allele-specific covalent inhibitor, received accelerated approval by the FDA in May 2021 and showed efficacy in certain subgroups during clinical trials." (PMID 35565305, 2022). "In other cancers, a proportion of KRAS-mutant cell lines resistant to trametinib was found to have a mesenchymal gene expression signature, and dasatinib has been reported to overcome mesenchymal transition–associated resistance to erlotinib in non–small cell lung cancers." (PMID 34737188, 2022). "Interestingly, KRAS independence had already been linked to EMT in lung cancer cell lines before." (PMID 34951114, 2022). "Furthermore, ABL1 can promote metastasis of lung cancer cells carrying also EGFR or KRAS mutations." (PMID 33596996, 2021). "Furthermore, KRAS mutations also have a predictive value in lung cancer." (PMID 35004317, 2021). "One example is that exogenous antioxidant treatment such as N-acetyl cysteine (NAC) or vitamin E in a water-soluble could promote metastasis process of KRas-mutated lung cancer cells, through reducing intracellular free heme that increases BACH1 proteins levels." (PMID 33809182, 2021). "Overall, these results indicate an association between oncogenic KRAS activation and PD-L1/PD-1 expression and their immunosuppressive roles, which support therapeutic strategies to target KRAS-mutant cancers through abrogation of the microenvironment in pancreatic and lung cancer." (PMID 33116132, 2020). "However, according to the results of the latest preclinical findings, the landscape of G12C KRAS-mutated lung cancer might change." (PMID 32548736, 2020). "Moreover, in lung cancer, KRAS mutations induce DDR1 expression to sustain tumorigenesis." (PMID 32117772, 2020). "To determine whether the synergistic effects on KRAS mutant lung cancer cells were associated with MAPK pathway, we treated a panel of KRAS(G12D) H838, KRAS(G12V) H441 and KRAS(G12S) H292cells and KRAS(WT) H838, H661and H1650 cells with AZ628 and BP-1-102 combination or BP-1-102 alone." (PMID 31484165, 2019). "In addition, DBS also provides an alternative tool to formalin-fixed paraffin-embedded cell blocks for biobanking to detect epidermal growth factor receptor (EGFR) or Kirsten rat sarcoma 2 viral oncogene homolog (KRAS) mutation for personalized target therapy in lung cancer patients." (PMID 30777078, 2019).
lung cancer (continued). "In colorectal and lung cancers, KRAS G12V mutations have been associated with a worse prognosis than KRAS G12D mutations, raising the possibility that particular amino acid substitutions might dictate specific transforming characteristics of oncogenic RAS alleles." (PMID 31398831, 2019). "While a great deal of attention is focused on the role of KRAS in the pathogenesis of lung cancer, little is known about the role of KRAS in regulating normal human airway epithelial function, nor of the direct impact of cigarette smoking, the major cause of lung cancer, on KRAS activation." (PMID 31399087, 2019). "Though this combination or single agent significantly caused the apoptosis of both KRAS mutant cancer cells and wild-type cells, it is observed that the two inhibitor’s combination obviously enhanced the ability of apoptosis induction in lung cancer cells harboring KRAS mutation." (PMID 31484165, 2019). "Thus, we further performed cleaved PARP immunoblot assay to investigate whether apoptosis induction caused growth inhibition in a panel of KRAS mutant lung cancer cells." (PMID 31484165, 2019). "i.e., KRAS mutation may be the key trigger of B7-H3 expression in lung cancer." (PMID 30513627, 2018). "The present study also revealed that EGFR mutations in advanced lung carcinoma were more frequently associated with intra-thoracic metastases to the lung and pleura, and the absence of lymphadenopathy and extranodal invasion, compared to the KRAS and ALK mutations." (PMID 27518729, 2016). "Interestingly, the cytokeratin AE1/AE3-stained xMD-procured lung carcinoma cells showed a 13-fold increase in KRAS mutation frequency (%) in comparison to the macrodissected heterogeneous cytospin (67.4% vs. 4.9%) and a 15-fold increase in the STK11 mutation frequency (%) (45.4% vs. 2.9%)." (PMID 26999048, 2016). "Finally, we note that the lung slice system could be utilized for studying the effects of other oncogenes known to be important in lung cancer such as mutated KRAS and EGFR and may also find application in the in vitro evaluation of cancer therapeutics." (PMID 25889156, 2015). "Key effector(s) of mutated KRAS in lung cancer progression and metastasis are unknown." (PMID 25956913, 2015). "In addition, xenograft experiments using the human AC cell line A549, which carries a KRAS mutation in the same amino acid as our mouse lung cancer model (G12S), showed increased tumour growth upon STAT3 knockdown, thus confirming the observations made in the mouse model." (PMID 25734337, 2015). "However, it is KRAS that has the highest mutation incidence in pancreatic cancer—twice its occurrence in cancer of the colon or small intestine, followed in decreasing order by endometrium and lung cancers and much lower in neoplasms of other tissues." (PMID 25265995, 2014). "Moreover, it was demonstrated that WT1 loss induced senescence and decreased proliferation of lung cancer cells downstream of oncogenic KRAS signalling.STAT3 is constitutively activated in many human tumors such as prostate, lung, brain, breast and pancreatic cancer." (PMID 23936312, 2013). "In addition to the important mechanistic role of let-7 miRNA in post-transcriptional regulation of KRAS gene expression, decreased let-7 miRNA expression has been associated with worse patient outcomes in lung cancer and may also affect radiosensitivity." (PMID 23202889, 2012).
lung cancer (continued). "Here we identify mSWI/SNF chromatin remodeling complexes as critical determinants of (EMT)-mediated KRAS inhibitor inefficacy and resistance in KRAS G12C lung cancers." (PMID 42124568, 2026). "Glutathione S-transferase zeta 1 (GSTZ1) is a metabolic enzyme that regulates cell metabolism; however, its role in KRAS-driven lung cancer remains underexplored." (PMID 42240478, 2026). "Similarly, organoid-immune co-cultures integrating patient-derived tumor cells, tumor-infiltrating lymphocytes, and PBMCs could elucidate the mechanism underlying immune-stromal crosstalk modulating KRAS G12Ci responses, though this remains under-explored in lung cancer." (PMID 41541668, 2026). "Mutations in several oncogenes are well-characterized driver events in various cancers, e.g., mutations in KRAS G12 residue in pancreatic and lung cancer, BRAF V600 in melanoma, and the EGFR L858 in lung cancer." (PMID 41567248, 2026). "Here, we show that in the context of oncogenic KRAS-driven lung cancer and strong neoantigen expression, tumor suppressor genotype dictates the degree of immune cell recruitment, positive selection of tumors with neoantigen silencing, and tumor outgrowth." (PMID 42297823, 2026). "Rapid progress has been made in the design of heterobifunctional proteolysis targeting chimeras (PROTACs) and molecular glue degraders, targeting key lung cancer culprits, such as KRAS." (PMID 42001483, 2026). "We used volumetric light sheet microscopy and biochemical approaches to investigate the role of BAMPs in regulating the molecular signaling of oncogenic KRAS in pancreatic and lung cancer models." (PMID 42039391, 2026). "Hit confirmation of pemigatinib was further assessed in an expanded 10 × 10 drug combination matrix with AMG 510 across KRAS G12C-mutant lung cancer cell lines, including the previously identified mesenchymal-like cell line LU99." (PMID 40788860, 2025). "For instance, in lung cancer, the co-activation of KRAS and c-MYC drives the recruitment of anti-inflammatory macrophages via CCL9 and IL-23, while simultaneously excluding T cells, B cells, and natural killer (NK) cells from the tumor site." (PMID 40333779, 2025). "These factors underscore the pressing need to explore the complexities of KRAS‐mutant lung cancer in order to improve therapeutic strategies and outcomes for patients." (PMID 41025426, 2025). "Mutant KRAS is a driver in lung cancer; furthermore, it is required for tumor maintenance in a mouse model of the disease, indicating a cell-autonomous role of oncogenic KRAS in cancer cells." (PMID 39782689, 2025). "Together, these findings confirm that RASON plays a critical role in KRAS-driven lung cancer, driving tumorigenesis and malignant progression." (PMID 40128846, 2025). "Our previous study has demonstrated that the expression of MEN1 is inactivated in approximately 23-27% of lung cancer cases, and this inactivation is correlated with KRAS-mediated DNA methylation at the MEN1 promoter region." (PMID 40057469, 2025). "The KRAS dataset consists of 3 models of lung cancer that are treated with a KRAS inhibitor at 4, 24, and 72 h, in addition to untreated cells at 0 h." (PMID 40209077, 2025). "Meanwhile, elevated LDHB levels in lung adenocarcinoma tissues are significantly associated with poor prognosis and reduced survival rates in cancer patients with KRAS-wild-type lung cancer." (PMID 41154605, 2025). "Since mitochondria are the primary source of ROS in cancer cells, mitochondria-targeted antioxidants were tested in mouse models of BRAF-driven melanoma and KRAS-driven lung cancer." (PMID 40646353, 2025).